S100A8 (S100 calcium binding protein A8)
Description:
S100A8 is a calcium- and zinc-binding protein which plays a prominent role in the regulation of inflammatory processes and immune response. It can induce neutrophil chemotaxis and adhesion. Predominantly found as calprotectin (S100A8/A9) which has a wide plethora of intra- and extracellular functions. The intracellular functions include: facilitating leukocyte arachidonic acid trafficking and metabolism, modulation of the tubulin-dependent cytoskeleton during migration of phagocytes and activation of the neutrophilic NADPH-oxidase. Also participates in regulatory T-cell differentiation together with CD69. Activates NADPH-oxidase by facilitating the enzyme complex assembly at the cell membrane, transferring arachidonic acid, an essential cofactor, to the enzyme complex and S100A8 contributes to the enzyme assembly by directly binding to NCF2/P67PHOX. The extracellular functions involve pro-inflammatory, antimicrobial, oxidant-scavenging and apoptosis-inducing activities. Its pro-inflammatory activity includes recruitment of leukocytes, promotion of cytokine and chemokine production, and regulation of leukocyte adhesion and migration. Acts as an alarmin or a danger associated molecular pattern (DAMP) molecule and stimulates innate immune cells via binding to pattern recognition receptors such as Toll-like receptor 4 (TLR4) and receptor for advanced glycation endproducts (AGER). Binding to TLR4 and AGER activates the MAP-kinase and NF-kappa-B signaling pathways resulting in the amplification of the pro-inflammatory cascade. Has antimicrobial activity towards bacteria and fungi and exerts its antimicrobial activity probably via chelation of Zn(2+) which is essential for microbial growth. Can induce cell death via autophagy and apoptosis and this occurs through the cross-talk of mitochondria and lysosomes via reactive oxygen species (ROS) and the process involves BNIP3. Can regulate neutrophil number and apoptosis by an anti-apoptotic effect; regulates cell survival via ITGAM/ITGB and TLR4 and a signaling mechanism involving MEK-ERK. Its role as an oxidant scavenger has a protective role in preventing exaggerated tissue damage by scavenging oxidants. Can act as a potent amplifier of inflammation in autoimmunity as well as in cancer development and tumor spread. The iNOS-S100A8/A9 transnitrosylase complex directs selective inflammatory stimulus-dependent S-nitrosylation of GAPDH and probably multiple targets such as ANXA5, EZR, MSN and VIM by recognizing a [IL]-x-C-x-x-[DE] motif; S100A8 seems to contribute to S-nitrosylation site selectivity. (Microbial infection) Upon infection by human coronavirus SARS-CoV-2, may induce expansion of aberrant immature neutrophils in a TLR4-dependent manner.
Synonyms: CFAG; MRP-8; p8; CAGA; MRP8; 60B8AG; CGLA; S100-A8; CP-10; L1Ag; MA387; NIF
Tractability: Small molecule: a structure with a bound ligand is known. Antibody: its Gene Ontology location is reachable by antibodies, with high confidence; UniProt places it where antibodies can reach, with medium confidence. PROTAC: its protein half-life has been measured.
Gene: Protein-coding gene on chromosome 1 (153,390,032 to 153,391,142, reverse strand). Ensembl gene ENSG00000143546.
Subcellular location: Secreted; Cytoplasm; Cytoplasm, cytoskeleton; Cell membrane
Subcellular location (Human Protein Atlas): Intermediate filaments; Cytosol; Predicted to be secreted
Pathways (Reactome):
Immune System: ER-Phagosome pathway; Metal sequestration by antimicrobial proteins; MyD88:MAL(TIRAP) cascade initiated on plasma membrane; Neutrophil degranulation; Regulation of TLR by endogenous ligand
Disease: IRAK4 deficiency (TLR2/4); MyD88 deficiency (TLR2/4)
Signal Transduction: RHO GTPases Activate NADPH Oxidases
Gene Ontology:
Molecular function: protein binding; arachidonate binding; calcium ion binding; calcium-dependent protein binding; microtubule binding; RAGE receptor binding; Toll-like receptor 4 binding; zinc ion binding
Biological process: autophagy; leukocyte migration involved in inflammatory response; neutrophil aggregation; neutrophil chemotaxis; peptidyl-cysteine S-nitrosylation; positive regulation of inflammatory response; positive regulation of intrinsic apoptotic signaling pathway; defense response to bacterium; defense response to fungus; endothelial cell migration; inflammatory response; positive regulation of cell growth; regulation of cytoskeleton organization; regulation of toll-like receptor signaling pathway; response to lipopolysaccharide; autocrine signaling; chronic inflammatory response; response to ethanol; response to zinc ion
Cellular component: calprotectin complex; cytosol; extracellular exosome; extracellular matrix; extracellular region; intermediate filament cytoskeleton; nucleus; S100A8 complex; cytoplasm; cytoskeleton; plasma membrane; secretory granule lumen
Genetic constraint (gnomAD): Loss-of-function variants: 4 observed, 5.24 expected, observed/expected ratio (o/e) 0.76, 90% interval 0.37 to 1.64. That is too few expected variants to judge how well the gene tolerates losing a copy. Missense variants: 96 observed, 117.24 expected, observed/expected ratio (o/e) 0.82, 90% interval 0.69 to 0.97. Synonymous variants: 41 observed, 47.37 expected, observed/expected ratio (o/e) 0.87, 90% interval 0.67 to 1.12.
Homologues: Orthologues: chimpanzee S100A8 (100% identical), macaque S100A8 (89% identical), dog S100A8 (73% identical), rabbit S100A8 (70% identical), pig S100A8 (69% identical), rat S100a8 (60% identical), mouse S100a8 (56% identical), zebrafish s100t (33% identical), zebrafish s100a10a (32% identical), zebrafish s100s (31% identical), tropical clawed frog s100a11 (25% identical). Paralogues in human: S100A12 (38% identical), S100A1 (35% identical), S100P (34% identical), CRNN (32% identical), S100B (32% identical), S100Z (30% identical), S100A4 (29% identical), S100A11 (28% identical), S100A10 (27% identical), S100A2 (27% identical), S100A5 (27% identical), S100A9 (27% identical), and 9 more.
Diseases named in the same sentence as S100A8 in open-access papers:
S100A8 is named in the same sentence as 593 diseases in open-access papers, as found by Europe PMC text mining. Sharing a sentence is not in itself a finding about the gene and the disease. The quoted sentences say what the papers report.
gastric cancer (560 papers, 2005 to 2026). A primary or metastatic malignant neoplasm involving the stomach. "Another in vitro study conducted on gastric cancer cell line underline that S100A8 and S100A9 expression are associated with a decrease in lymph node metastasis and these proteins can be used as biomarkers in gastric adenocarcinoma." (PMID 25298751, 2014). "On the other hand, upregulated S100A8 was correlated with a better prognosis in all gastric cancer patients." (PMID 38361783, 2024). "In any case, besides the results in sarcoma and head and neck cancer, other authors reported associations of S100A9 inflammatory cells with good prognosis in gastric cancer, as well as therapeutic interventions with recombinant S100A8 in lung cancer." (PMID 39563958, 2024). "Levels of S100A8/A9 are also elevated in the plasma of patients with gastric cancer and glioblastoma and positively correlate with stage of disease." (PMID 36831371, 2023). "In human gastric cancer, serum levels of S100A8 and A9 correlate with MDSC levels, MDSCs’ suppressive potency, and cancer stage." (PMID 36831371, 2023). "S100A8/9 are found ubiquitously in most tumours and increased S100A8/9 has also been shown to prevent the differentiation of myeloid progenitor cells and deactivation of T-cell in breast, ovarian, and gastric cancer." (PMID 32121014, 2020). "In human gastric cancer cell line SNU484, S100A8 and S100A9 inhibition was linked with decreased of invasive and migratory phenotypes of tumoral cells." (PMID 25298751, 2014). "Further investigation found that S100A8 distribution in human gastric cancer tissues was similar to S100A9." (PMID 22838504, 2012). "It was reported previously that S100A9 is up-regulated in conjunction with S100A8 in many cancers, including gastric cancer, prostate cancer, and colorectal cancer." (PMID 20096140, 2010). "S100A8 and S100A9 which form a heterodimer complex 90 are up-regulated in many cancers and have been implicated in the metastatic process including gastric cancer, prostate cancer, colorectal cancer, and breast cancer." (PMID 19691830, 2009). "Additionally, an increased presence of polymorphonuclear myeloid-derived suppressor cells (PMN-MDSC) in gastric cancer hampers the anti-cancer immune response through S100A8/A9." (PMID 38093319, 2023). "Moreover, in patients with gastric cancer high plasma levels of S100A8/A9 correlated with the increased population of myeloid cells." (PMID 37347110, 2023). "Furthermore, the levels of S100A8/A9 are markedly elevated in various cancer types, including non-small cell lung cancer, gastric cancer, colorectal cancer, pancreatic cancer, and prostate cancer." (PMID 38093319, 2023). "Taken together, the differential expression and subcellular localization of S100A9, S100A8 and S100A8/A9 in various tissues may implicate their different roles in gastric cancer or chronic gastritis environment." (PMID 22838504, 2012). "The differential expression and subcellular localization of S100A9 and S100A8/A9 in various tissues may indicate that only S100A9 plays a role in gastric cancer development." (PMID 22838504, 2012). "It was found that CXCL1/CXCR2 recruits PMN-MDSCs, and S100A8/A9 increases CXCL1 expression in gastric cancer (GC) through the TLR4/p38 MAPK/NF-κB pathway." (PMID 39990210, 2025). "To confirm this hypothesis, we further investigated the subcellular localization pattern of S100A9, S100A8 and S100A8/A9 heterodimer expression by performing immunofluorecence staining in a tissue microarray including 23 cases of gastric cancer and 57 cases of chronic gastritis." (PMID 22838504, 2012). "Our findings demonstrate that salivary proteins, particularly S100A8, S100A9, CST4, and CST5, hold significant potential as non-invasive biomarkers for gastric cancer detection." (PMID 41164825, 2025). "PRM analysis confirmed the upregulation of S100A8 and S100A9 in saliva from patients with gastric cancer." (PMID 41164825, 2025).
gastric cancer (continued). "Given the direct correlation between S100A8/A9 levels, MDSC levels, and tumor progression, studies in human prostate cancer, colon cancer, and gastric cancer have concluded that S100A8 and/or A9 are early biomarkers and are diagnostic for cancer progression." (PMID 36831371, 2023). "On the other hand, we have observed the upregulation of genes that are involved in the proliferation, migration, and invasion of cancer cells in colorectal and gastric cancer (ANGPTL4, S100A8, LINC00668)." (PMID 35625760, 2022). "It is suggested that S100A8 and S100A9 can activate p38 mitogen-activated protein kinase (MAPK)/nuclear factor kappa B in inflammation and gastric cancer cells invasion." (PMID 35397606, 2022). "S100A8/A9 heterodimer from PMN-MDSCs inhibits glycolysis and proliferation of CD8+ T cells, and PMN-MDSCs are upstream suppressive cells for CD8+ T cells exhaustion, inducing ICIs resistance of gastric cancer." (PMID 41051525, 2025). "In the present study, a subcluster of neutrophils with high-activity phenotypes accounted for a major proportion of PB samples after treatment, which also highly expressed well-known tumor-promoting genes of gastric cancer including MMP9, S100A8, S100A9, PORK2, and TGF-β1." (PMID 37333017, 2023). "Furthermore, S100A8 and S100A9 are upregulated in a variety of cancers such as lung cancer, prostate cancer, colon cancer, stomach cancer, and breast cancer." (PMID 34934042, 2021). "For instance, p38 MAPK and ERK1/2 was shown to be activated and suppressed, respectively, following the binding of S100A8/A9 to RAGE in gastric cancer cells whilst in colon cancer cells, S100A8/A9 induced the activation of ERK1/2 and JNK but not p38 MAPK." (PMID 27547188, 2016). "Surprisingly, S100A8 cell count in gastric cancer tissues did not correlate with most of clinicopathological features or patient survival." (PMID 22838504, 2012). "Consistent with the results of immunohistochemistry, S100A8/A9 was not expressed in any cells of gastric cancer tissues, while expression of S100A8/A9 partly overlapped with the S100A9 in inflammatory cells of gastritis tissues." (PMID 22838504, 2012). "Remarkably, expression of S100A8/A9 heterodimerization complex was apparently absent in gastric cancer tissues, while it was detected in gastritis and control inflammation tissues such as appendicitis." (PMID 22838504, 2012). "In this study, we used iTRAQ and PRM-based quantitative proteomics to detect four saliva protein biomarkers of gastric cancer, including S100A8, S100A9, NUCB2, and CST4, which make them potential novel biomarkers for the noninvasive diagnosis of GC." (PMID 41164825, 2025). "However, at lower concentrations, S100A8/A9 treatment increased the migration and invasion of gastric cancer cells without affecting cell proliferation and viability." (PMID 39329929, 2024). "Next, we further examined the expression of S100A8, a close family member of S100A9 and the heterodimerization form S100A8/A9 in both gastric cancer tissues and adjacent non-tumor chronic gastritis tissues in the gastric cancer specimens by performing immunohistochemistry." (PMID 22838504, 2012). "S100A8 was not expressed in all gastric cancer cells and normal gastric mucosa." (PMID 22838504, 2012). "In gastric cancer tissues, both S100A9 and S100A8 proteins were detected in the tumor-infiltrating inflammatory cells, while no S100A8/A9 heterodimer was found in any cases." (PMID 22838504, 2012). "In addition, the cell count of S100A8, a dimerization partner of S100A9, was not correlated with the clinicopathological features or overall survival in patients with gastric cancer." (PMID 22838504, 2012).
gastritis (163 papers, 2005 to 2025). Inflammation of the stomach. "Similarly to the pattern of S100A9, S100A8 was expressed exclusively in inflammatory cells infiltrating both tumor tissues and adjacent gastritis tissues." (PMID 22838504, 2012). "The inflammatory cells infiltrating cancer were S100A8/A9 negative, while those in gastritis were positive." (PMID 22838504, 2012).
COVID-19 (142 papers, 2020 to 2025). A disease caused by infection with severe acute respiratory syndrome coronavirus 2. "Serum S100A8/A9 levels were also higher in COVID-19 patients than those in healthy controls and associated with the severity of COVID-19." (PMID 39516272, 2025). "For example, mice treated with an S100A8 neutralizing agent were protected from systemic inflammation and fatal immune dysregulation in a model of cytokine storms associated with COVID-19." (PMID 40599378, 2025). "S100a8/a9 expression has been associated with numerous inflammatory states, including severe COVID-19." (PMID 40937719, 2025). "S100A8/A9 have been proposed as a potential diagnostic biomarker of COVID-19, since it has the ability to distinguish between mild and severe disease states." (PMID 39183264, 2024). "The dysregulation of S100A8/A9 expression has been associated with severe inflammatory reactions, such as those observed in critical cases of Coronavirus Disease 2019 (COVID-19), especially during the initial stages of infection." (PMID 39768135, 2024). "Several studies have shown a correlation between S100A8/A9 and disease severity of COVID-19 with increased S100A8/A9 levels being associated with poor clinical outcomes such as significantly reduced survival time." (PMID 37041310, 2023). "Overall, our study provides a deeper understanding of how peripheralS100A8/A9 levels relate to COVID-19 patient outcomes in the U.S. andoffers insight into the association between urine and serum S100A8/A9levels." (PMID 37787461, 2023). "Severe COVID-19 is associated with a high circulating level of calprotectin, the S100A8/S100A9 alarmin heterodimer." (PMID 35644124, 2022). "The inflammatory mediator of EN-RAGE encoded by S100A12 was significantly correlated with COVID-19, and S100A8, S100A9, IRF3, IFI6, IFITM1, and IFITM3 have been reported to elicit autoinflammatory and autoimmune conditions in response to SARS-CoV-2 infection." (PMID 35172892, 2022). "Serum S100A8/A9 levels in COVID-19 patients are linked to severity and in-hospital mortality and early indicator of respiratory failure." (PMID 34239729, 2021). "Higher blood frequency of NETs and neutrophil activation markers including S100A8/A9 are observed in COVID-19 cases associated with thrombosis and in COVID-19 with severe pulmonary outcomes." (PMID 34239729, 2021). "Equally, monocytes with low expression of HLA-DR and high expression of S100A8, A9, and 12 are strongly associated with severe COVID-19." (PMID 34239729, 2021). "Alarmins are possible danger signals associated with COVID-19 and comorbidities, and S100A8/A9, high mobility group box 1 (HMGB1), and histones are considered potential therapeutic targets." (PMID 34682694, 2021). "In conclusion, our data suggest that induction of elevated levels of alpha-defensins and S100A8/A9 is associated with poor disease outcome in COVID-19 patients." (PMID 34746027, 2021). "Inhibition of S100A8/A9 has shown promise in attenuating COVID-19-related pneumonia in experimental models." (PMID 37828990, 2023). "Monocytic MDSCs, a subtype of myeloid cells characterized by reduced MHC-II expression and increased neutrophil activation-associated genes (e.g., S100A8/A9), was identified to be significantly elevated in COVID-19 patients with encephalopathy, especially acute necrotizing encephalopathy." (PMID 37848421, 2023). "In addition, we found other cell-death-associated proteins (CD274, HTATIP2, and S100A8) in the patients, which supports the observation that severely diseased COVID-19 patients develop thrombocytopenia." (PMID 37681923, 2023). "Our results help direct future diagnostic and prognostic investigationsof S100A8/A9 during COVID-19 and improve the field’s understandingregarding the utility of urine S100A8/A9 as a potential biomarker,especially in diseases that currently use serum S100A8/A9 as a markerof patient outcomes." (PMID 37787461, 2023).